TPO (thyroid peroxidase)
Diseases named in the same sentence as TPO in open-access papers (continued):
Sharing a sentence is not in itself a finding about the gene and the disease.
bipolar disorder (5 papers, 2016 to 2023). A disorder of the brain that causes unusual shifts in mood, energy, activity levels and the ability to carry out day-to-day tasks. "Several cross-sectional studies demonstrated that autoantibodies to thyroid peroxidase (TPO-Abs) are about 1–2 times more prevalent in patients with bipolar disorder (BD) than in the general population." (PMID 28108944, 2017). "At this juncture, serum TPO-Abs were found more frequently in patients with bipolar disorder if compared with other patients and, moreover, were related to the genetic vulnerability to develop bipolar disorder." (PMID 27688922, 2016). "In patients with bipolar disorder, regardless of the use of lithium (having “anti-thyroid” properties), the presence of Anti-TPO and AHT is also more frequent." (PMID 35455388, 2022). "Also, the offspring of people with bipolar disorder have a higher incidence of Anti-TPO, even if they do not have mental disorders." (PMID 35455388, 2022). "Also offspring of patients with a bipolar affective disorder have a higher prevalence of TPO-Abs, even if they are not affected by the psychiatric disorder." (PMID 27092550, 2016).
Graves’ orbitopathy (5 papers, 2023 to 2025). "In turn, selenium supplementation in patients with AITD, particularly those with HT, reduces anti-TPO levels, improves quality of life, and delays disease progression in patients with Graves’ orbitopathy." (PMID 38534778, 2024). "TPO gene SNPs were also evaluated for their role in Graves orbitopathy (GO) pathogenesis." (PMID 38542286, 2024).
myelofibrosis (5 papers, 2018 to 2025). A partial or complete replacement of the bone marrow stroma by fibrous tissue. "This stands in contrast to the documented side effects associated with other approved TPO-RAs, such as romiplostim, eltrombopag, and avatrombopag, where incidences of thromboembolic events, hepatotoxicity, cataracts, prolonged QT intervals, and myelofibrosis have been noted." (PMID 38842566, 2024). "The incidences of thromboembolic events, hepatotoxicity, cataracts, prolonged QT interval, and myelofibrosis in patients treated with other approved TPO-RAs are worth mentioning, with such drugs including romiplostim, eltrombopag and avatrombopag." (PMID 33632264, 2021). "We combined our murine model of TPO overexpression‐induced MPN/myelofibrosis with a knockout of S100a9 in HSPCs, and transplanted lethally irradiated WT recipients with either WT (here referred to as S100a9+/+) or S100a9−/− ckit+ HSPCs overexpressing TPO or its EV control." (PMID 40823315, 2025). "4D7 selectively bound to cells co‐expressing mutant CALR and thrombopoietin receptor (TpoR) and blocked JAK‐STAT signalling, TPO‐independent proliferation and megakaryocyte differentiation of mutant CALR myelofibrosis progenitors by disrupting the binding of CALR dimers to TpoR." (PMID 35156745, 2022).
myocardial infarction (5 papers, 2017 to 2025). Gross necrosis of the myocardium, as a result of interruption of the blood supply to the area, as in coronary thrombosis. "In an observational study of postmenopausal women in the Netherlands, those with SCH had an increased prevalence of myocardial infarction [odds ratio (OR) 2.3, 95% confidence interval (CI) 1.3–4.0]; this risk was even higher among those with positive serum TPO antibodies (OR 3.5, 95% CI 1.7–7.4)." (PMID 33193104, 2020). "We showed in the in vivo rat model of myocardial ischemia–reperfusion injury that GF/TPO NPs are able to target the area of myocardial infarction as evidenced by the significantly greater level of fluorescence." (PMID 35683129, 2022). "Compared with euthyroid individuals, the HR for incident myocardial infarction was 0.90 (95% CI 0.47–1.74) among women with TSH of ≥7 mIU/L and positive serum TPO antibodies." (PMID 33193104, 2020).
myositis (5 papers, 2014 to 2025). "Autoantibodies recognizing SRP54, a myositis-associated autoantigen, increased by over 4-fold between the first and second time points in individual AA19 who also carried anti–PDC-E2 and anti–TPO CTD-AAbs at baseline." (PMID 36752204, 2023).
placental abruption (5 papers, 2013 to 2025). Vaginal bleeding preceding the 20th week of gestation. "The possible effect of TPO antibodies in perinatal and obstetric outcomes was studied in ~17,000 euthyroid thyroid peroxidase antibody positive and negative women which revealed a fourfold increase in the incidence of placental abruption." (PMID 23691429, 2013).
Portal vein thrombosis (5 papers, 2019 to 2025). Thrombosis of the portal vein and/or its tributaries, which include the splenic vein and the superior and inferior mesenteric veins. "Moreover, TPO-RAs have reported long-term remission after treatment discontinuation in 30–50% of responders with a good safety profile, whereas splenectomy is an irreversible procedure that increases the risk of life-long infectious complications and portal vein thrombosis." (PMID 39210059, 2024). "We describe an instructive case of ITP that was complicated by severe portal vein thrombosis during treatment with eltrombopag, an oral thrombopoietin-receptor agonist (TPO-RA) drug, plus prednisolone (PSL) concomitant splenectomy." (PMID 34589366, 2021). "Particularly in liver surgery, liver function disorder (15%) and portal vein thrombosis (4%) are adverse effects of TPO-RA and may have a serious influence on preoperative liver function." (PMID 30969381, 2019).
schizophrenia (5 papers, 2016 to 2024). A major psychotic disorder characterized by abnormalities in the perception or expression of reality. "The levels of Tg-Ab, TPO-Ab and TSHrAb antibodies increased significantly (30.93±3.87, 10.33±1.78 and 3.76±0.055 pg/ml) in the newly diagnosed patients of schizophrenia." (PMID 28083028, 2016). "TPO antibodies are also found in 10% of patients with psychiatric admissions (affective disorders, schizophrenia, dementia, other psychosis and personality disorders), up to 28% of patients with degenerative dementia and 14% of patients with genetic cerebellar ataxias." (PMID 34061124, 2021). "The levels of antibody titer represent that thyroid peroxidase-antibody (TPOAb), thyroid-stimulating hormone receptor-antibody (TSHrAb), and thyroglobulin-antibody (TgAb) were raised in the patients suffering from schizophrenia along with thyroid dysfunction." (PMID 33995058, 2021).
autism (4 papers, 2016 to 2025). Persistent deficits in social interaction and communication and interaction as well as a markedly restricted repertoire of activity and interest as well as repetitive patterns of behavior. "The prevalence of maternal anti-thyroid peroxidase antibodies was significantly increased in pregnancies giving rise to autism cases compared with controls." (PMID 32423096, 2020). "The odds of autism were increased by nearly 80% among the offspring of mothers who had positive anti-thyroid peroxidase antibodies during pregnancy, compared with mothers negative for this autoantibody." (PMID 32423096, 2020). "The odds of childhood autism were increased by nearly 80% among offspring of mothers who were positive for anti thyroperoxidase antibodies (TPO-Ab+) during pregnancy, compared to mothers negative for this autoantibody." (PMID 27458336, 2016).
cerebellar ataxia (4 papers, 2020 to 2023). A neurological syndrome characterized by clumsy and uncoordinated movement of the limbs, trunk, and cranial muscles. "She initially presented with rapid-onset progressive symptoms of cerebellar ataxia (movement incoordination, dysmetria, and balance problems) and had elevated serum anti-thyroid peroxidase antibodies." (PMID 37900529, 2023). "A neurological examination revealed nystagmus, intention tremor, and ataxia, and anti-thyroid peroxidase and anti-thyroglobulin levels were found to be elevated." (PMID 33477892, 2021).
liver disease (4 papers, 2013 to 2024). "Neither gender, liver disease, phase of the disease, previous history of neoplasia or VE, nor exposure or responses to previous lines of therapy were associated with the choice of TPO-RA (P > 0.05)." (PMID 31723222, 2019). "High serum levels of anti-TPO were found in two cases with minor and transitory thyroid function test result alterations, and AMA antibodies were positive in one case presenting mild elevations of serum liver enzymes without clinical manifestations of liver disease." (PMID 24209578, 2013). "However, none of the ANA-positive participants met the 1982 ACR criteria necessary for the diagnosis of SLE, none with increased anti-TPO antibodies showed clinical manifestations of thyroid dysfunction and none of the AMA-positive individuals had clinical manifestations of liver disease." (PMID 24283458, 2013).
lung cancer (4 papers, 2011 to 2022). A malignant neoplasm involving the lung. "In addition, lung cancer cells (without absorption of natural iodide) transfected with NIS or NIS/TPO, a supplement of KI (30 mM), induced apoptosis only in cells transfected with NIS/TPO, indicating that oxidation of I− by TPO is required to exert apoptotic effects." (PMID 33513754, 2021).
ovarian carcinoma (4 papers, 2013 to 2021). A malignant neoplasm originating from the surface ovarian epithelium. "Thrombopoietin receptor MPL (TPO-R), a major regulator of megakaryocytopoiesis and platelet formation, is a proto-oncogene whose ligand (TPO) has been recently identified as a novel candidate marker for ovarian cancer diagnosis and is associated with a poor survival." (PMID 31276486, 2019). "Thrombopoietin receptor MPL (TPO-R) is a proto-oncogene whose ligand (TPO) has been recently promoted as a marker for ovarian cancer and with existing agonists: found higher levels associated with more advanced cases and levels of serum thrombopoietin decreased after primary treatment." (PMID 26622942, 2015). "In OVC Module 8, STAT5B-STAT3 gene pair is activated in ovarian cancer, interacts with each other, and is involved in many pathways including Jak-STAT signaling, RAS signaling, Chemokine signaling, EGF, IL10, PDGF, and TPO pathways." (PMID 23940583, 2013). "After 21 days of induction with SFTG36 (SCF, FLt-3L, TPO, GM-CSF, IL-3 and IL-6), IS721 (IGF-1, SIS3, IL-7 and IL-21) and IL-15/Hsp70 media, NK cells phenotypes were studied and their cytotoxicity against K562 human erythroleukemia cells and SKOV3 ovarian carcinoma cells was analyzed." (PMID 34098947, 2021).
postpartum depression (4 papers, 2014 to 2022). A type of clinical depression that occurs after childbirth. "Twenty-one full text articles were examined as they were thought to contain data that could address our objective (associations between anti-TPO during pregnancy or the puerperium or postnatal depression)." (PMID 35351167, 2022). "In summary, the studies comprising this systematic review suggest that associations may exist between anti-TPO-positive status during gestation and postpartum depression." (PMID 35351167, 2022). "We and others have reported that the presence of TPO autoantibodies alone may be associated with postpartum depression." (PMID 25405057, 2014). "The longitudinal pattern of self-reported postpartum depression in the positive anti-TPO group was similar to the typical course of anti-TPO in the postpartum period." (PMID 35351167, 2022). "Of these studies, seven reported on the relationships between anti-TPO during pregnancy and postnatal depression, and five investigated the links between anti-TPO during the postpartum period and postnatal depression." (PMID 35351167, 2022).
Sjögren’s syndrome (4 papers, 2021 to 2025). "Three individuals were ultimately diagnosed with autoimmune encephalopathy with anti-thyroid encephalitis (anti-thyroid peroxidase antibodies), Sjogren’s syndrome, and catastrophic antiphospholipid syndrome." (PMID 37077567, 2023).
Thromboembolism (4 papers, 2018 to 2025). The formation of a blood clot inside a blood vessel that subsequently travels through the blood stream from the site where it formed to another location in the body, generally leading to vascular occlusion at the distant site. "Patients with ITP have a 3- to 4-rfold higher risk of thromboembolism than healthy individuals, which is further increased by treatment with TPO-RAs or splenectomy." (PMID 39873866, 2025). "TPO-RAs such as eltrombopag are associated with an increased risk of thromboembolism, on top of the increased risk of thromboembolic events seen in elderly patients with ITP." (PMID 36393999, 2022). "Although these AEs were not reported in the RCTs due to small sample size, physicians should be cautious when administering TPO-RAs to patients with higher risk of thromboembolism, especially for ELT." (PMID 29330464, 2018). "The physicians should still be cautious when administering TPO-RAs to patients with higher risk of thromboembolism, especially for ELT." (PMID 29856837, 2018).
toxic multinodular goiter (4 papers, 2014 to 2023). "In conclusion, this study identified ten TPO mutations associated with nontoxic and toxic goiter that have not been yet reported in Iraq, and most of them are detected among females (90 %) and adults aged between 30 to 50 years old (80 %)." (PMID 24482635, 2014). "TSH: thyroid stimulating hormone; fT4: thyroxine; fT3: triiodothyronine; TRAB: TSH receptor antibody; Anti-TG: anti-thyroglobulin; Anti-TPO: anti-thyroid peroxidase; TMNG: toxic multinodular goiter." (PMID 31066760, 2019).
viral infection (4 papers, 2015 to 2024). "Autoantibodies including anti-SRP54 and anti-TPO developed in 2 patients with influenza and remained elevated approximately 1 month after their first hospital visit, suggesting that viral infection triggered autoantibody development." (PMID 36752204, 2023).
vitamin B12 deficiency (4 papers, 2019 to 2024). A disease characterized by low serum levels of vitamin B12, either inherited or acquired. "On correlating vitamin B12 levels with thyroid autoantibodies, 78.6% of patients with raised anti-TPO antibodies were found to have vitamin B12 deficiency (p = 0.01), while 78% of patients with raised anti-Tg antibodies had vitamin B12 deficiency (p = 0.07)." (PMID 37767262, 2023). "Of patients with raised anti-TPO antibodies, 78.6% had vitamin B12 deficiency (p = 0.01), while 78% of patients with raised anti-Tg antibodies were vitamin B12 deficient (p = 0.07)." (PMID 37767262, 2023). "In other words, 78.6% of patients in our study with raised anti-TPO antibodies were found to have vitamin B12 deficiency (p = 0.01)." (PMID 37767262, 2023). "We found that 64.7% of patients with vitamin B12 deficiency had raised anti-TPO antibodies." (PMID 37767262, 2023). "The presence of positive anti-TPO antibodies and the degree of elevation in TSH levels may exacerbate vitamin B12 deficiency in SCH patients." (PMID 38957249, 2024).
anxiety disorder (3 papers, 2004 to 2023). A category of psychiatric disorders which are characterized by anxious feelings or fear often accompanied by physical symptoms associated with anxiety. "This study seems to indicate an association between the presence of a lifetime diagnosis of mood or anxiety disorder and sleep disturbance and anti-TPO+." (PMID 16285879, 2005). "This study indicates an association between the presence of a lifetime diagnosis of mood or anxiety disorder and anti-TPO+." (PMID 15317653, 2004). "The present study indicates an association between the presence of a lifetime diagnosis of mood or anxiety disorder and anti-TPO+ in a general population sample which had not been selected from medical or psychiatric health facilities." (PMID 15317653, 2004).
benign thyroid tumors (3 papers, 2015 to 2021). "Although Galectin-3 and MC are frequently expressed in PTC, and TPO and CD56 are frequently expressed in benign thyroid tumor, the sensitivity of these markers remains unsatisfactory." (PMID 30005075, 2018). "The has-miR-200a-5p as an overexpressed molecule is a sensitive biomarker and could be combined with immunohistochemical markers such as TPO, CD56, Galectin 3, MC, CK19, and BRAF both to detect and to distinguish between PTC and benign thyroid tumor with papillary hyperplasia." (PMID 35186709, 2021).
diabetic ketoacidosis (3 papers, 2023 to 2024). The metabolic condition resulted from uncontrolled diabetes mellitus, in which the shift of acid-base status of the body toward the acid side because of loss of base or retention of acids other than carbonic acid is accompanied by the accumulation of ketone bodies in body tissues and fluids. "Anti-TransGlut IgA: anti- transglutaminase IgA antibody, TPOAb: thyroid peroxidase antibodies, TRAb: thyrotropin receptor antibodies, TgAb: thyroglobulin antibodies, DKA: diabetic ketoacidosis, N/A: information not available, F: Female, M: Male." (PMID 37542216, 2023).
endometriosis (3 papers, 2016 to 2020). The growth of functional endometrial tissue in anatomic sites outside the uterine body. "It has been shown that the presence of TPO-Ab in particular is associated with an increased risk of PCOS and endometriosis, and varying aetiologies based on the inclusion criteria and antibodies present may have influenced results." (PMID 33239046, 2020).
female infertility (3 papers, 2021 to 2024). Diminished or absent ability of a female to achieve conception. "In a biochemically euthyroid patient, the only scenario where L-T4 was considered by a significant number of participants was female infertility with high TPO antibody levels." (PMID 34938274, 2021). "Interestingly, 49.5% reported that treatment with thyroid hormone was never indicated for biochemically euthyroid patients, while almost the same proportion (47.3%) of the Swedish respondents would consider L-T4 treatment in case of high levels of TPO-antibodies and female infertility." (PMID 34938274, 2021). "Significant predictors of female subfertility were HDL-C < 50 mg/dL and anti-TPO positivity." (PMID 37763034, 2023). "Therefore, to detect more accurate effect of TSH level < 2.5 mIU/L in female infertility, a 3–6 months treatment period is suggested for future studies, in order to reduce TSH below 2.5 mIU/L in these women on the ART outcomes and the effect of anti-TPO." (PMID 39091424, 2024).
hyperlipidemia (3 papers, 2015 to 2023). "In the univariate analysis, hyperlipidemia and high BMI scores were correlated with poor TPO-agent response (P = 0.029 and P = 0.002, respectively)." (PMID 37784127, 2023). "Patients with hyperlipidemia had worse TPO agent reactivity than those with normal lipid levels (58.9% vs. 75.4%, P = 0.04, and 39.5% vs. 69.5%, P = 0.04 after PSM)." (PMID 37784127, 2023). "Furthermore, hyperlipidemia and high BMI scores were correlated with poor TPO-agent responses." (PMID 37784127, 2023).
lymphopenia (3 papers, 2019 to 2023). Reduction in the number of lymphocytes. "She had leukopenia (3300/mm3) and lymphopenia (900/mm3), very low B12 (67 ng/dL), and high anti-thyroid peroxidase antibody (628 U/ml) with normal thyroid function tests." (PMID 37235056, 2023).
nephrotic syndrome (3 papers, 2021 to 2025). A collection of symptoms that include severe edema, proteinuria, and hypoalbuminemia; it is indicative of renal dysfunction. "While there is evidence of Thyroglobulin antibody affecting renal function, leading to conditions like glomerulonephritis and nephrotic syndrome, data on the impact of Anti Thyroid peroxidase antibody (Anti-TPO) on renal function is limited." (PMID 40937419, 2025).
Pendred syndrome (3 papers, 2014 to 2020). Pendred syndrome (PDS) is a clinically variable genetic disorder characterized by bilateral sensorineural hearing loss and euthyroid goiter. "One of the patients in Taiwan with a compound heterozygous mutation of c.1079C>T and c.IVS7-2A>G was positive for both the perchlorate discharge test (PDT) and anti-thyroid peroxidase antibodies (anti-TPO Abs), suggestive of Pendred’s syndrome." (PMID 26252218, 2015).